CXCL13 (C-X-C motif chemokine ligand 13)
Diseases named in the same sentence as CXCL13 in open-access papers (continued):
Sharing a sentence is not in itself a finding about the gene and the disease.
breast tumors (8 papers, 2015 to 2024). "In a multivariable analysis high breast tumor median CXCL13 content was independently associated with favorable DDFS (HR 0.44, 95% CI 0.29–0.67; P ≤ 0.001), whereas CD4 content and FOXP3 content were not (HR 1.89, 95% CI 0.80–1.78; P = 0.396; and HR 1.20, 95% CI 0.78–1.84; P = 0.400, respectively)." (PMID 29482642, 2018). "Gynecologic and breast tumors (Pan-Gyn) exhibit similar characteristics, and the role of CXCL13 in anti-tumor immunity and it’s potential as a biomarker for immune checkpoint blockade (ICB) therapy have been gradually revealed." (PMID 38459390, 2024). "CXCL13, a chemokine that strongly attracts B cells, is produced by Tfh cells as well as follicular dendritic cells in breast tumor tissues and plays a pivotal role in enhancing antitumor humoral immunity." (PMID 33506656, 2021). "We found that the high concentration of serum HER2‐AAb was associated with the accumulation of B cells, plasma cells, and CXCL13‐positive ICs in breast tumors and of follicular CD4‐positive ICs, which presumably represented Tfh cells, in the axillary lymph nodes." (PMID 33506656, 2021). "A positive correlation was found between the expressions of CXCL13 and CXCR5 in breast tumors." (PMID 31354634, 2019). "In this study, an increase in the CXCL13‐positive ICs in the high HER2‐AAb group indicates that the CXCL13‐positive ICs in the tumor stroma and the follicular CD4‐positive ICs found in the SLOs both stimulated the maturation of B cells and helped them to migrate to the breast tumor stroma." (PMID 33506656, 2021).
myasthenia gravis (8 papers, 2010 to 2024). Myasthenia gravis (MG) is a rare, clinically heterogeneous, autoimmune disorder of the neuromuscular junction characterized by fatigable weakness of voluntary muscles. "For instance, overexpression of CXCL13 rescued apoptosis in myasthenia gravis." (PMID 38459390, 2024). "The formation of CXCL13/CXCR5‐derived tertiary lymphoid structures has been associated with the evolution of a divergent range of diseases, including MS, myasthenia gravis, Sjögren's disease, RA, bullous pemphigoid, Graves thyroiditis, and infectious diseases." (PMID 35702353, 2022). "A similar role of CXCL13 and/or CXCR5 in regulating the formation of ectopic lymphoid structures was subsequently found in myasthenia gravis, Sjögren's syndrome, and SLE." (PMID 35702353, 2022).
neuromyelitis optica (8 papers, 2020 to 2022). A rare inflammatory disease of the central nervous system characterized mainly by attacks of uni- or bilateral optic neuritis (ON) and acute myelitis. "Especially, CSF CXCL13 levels were found to be increased in neuromyelitis optica (NMO) compared with MS patients and were related to the NMO disease activity indicated by relapse rate and Expanded Disability Status Scale (EDSS) scores." (PMID 36611365, 2022).
osteosarcoma (8 papers, 2019 to 2024). A usually aggressive malignant bone-forming mesenchymal neoplasm, predominantly affecting adolescents and young adults. "Interestingly, CXCL13 expression was upregulated in migration-prone MG-63 cells, indicating that CXCL13 levels are associated with the migratory ability of osteosarcoma cells." (PMID 32847038, 2020). "Given the high expression of MICA/B and CXCL13, human osteosarcoma cell lines constitute the perfect avenue for studying our CAR system expressing NKG2D, CXCR5, and IL-7." (PMID 39450160, 2024). "Signature (ZNF583, CGNL1, CXCL13) was developed to predict overall survival in osteosarcoma patients, targeting the anoikis subcluster." (PMID 37980450, 2023). "The results revealed elevated levels of CGNL1 and CXCL13 in osteosarcoma cell lines, while ZNF583 was markedly downregulated." (PMID 37980450, 2023). "In the TARGET‐osteosarcoma cohort, we observed a strong correlation between the LAMP3_DC gene signature and the CD4_C6_FOXP3 and CD4_C5_CXCL13 cellular gene signatures." (PMID 36305631, 2022). "The PLCβ, PKCα, and c-Src signaling pathways appear to play a role in CXCL13-facilitated VCAM-1-dependent osteosarcoma cell migration." (PMID 32847038, 2020). "Although CXCL13-regulated cancer cell migration and metastasis has been reported in some cancers, the effect of CXCL13 in the motility of osteosarcoma cells remains uncertain." (PMID 32847038, 2020). "Activation of PLCβ, PKCα, and c-Src appears to be necessary for CXCL13-induced NF-κB activation in human osteosarcoma cells." (PMID 32847038, 2020). "Here, we found that CXCL13 increases the migration and invasion potential of three osteosarcoma cell lines." (PMID 32847038, 2020). "PLCβ, PKCα, and c-Src siRNAs confirmed the reversal of CXCL13-induced promotion of osteosarcoma cell migratory activity." (PMID 32847038, 2020). "Treatment of osteosarcoma cells with CXCL13 facilitated IKK, IκBα, and p65 phosphorylation in a time-dependent manner." (PMID 32847038, 2020). "Transfection of cells with VCAM-1 siRNA reduced levels of VCAM-1 expression and CXCL13-induced promotion of osteosarcoma cell migration, indicating that CXCL13 facilitates VCAM-1-dependent osteosarcoma cell migration." (PMID 32847038, 2020). "Here, we found that CXCR5 siRNA and CXCR5 antibody markedly inhibited CXCL13-induced VCAM-1 expression and cell migration, suggesting that the CXCL13/CXCR5 interaction regulates VCAM-1-mediated migration of human osteosarcoma cells." (PMID 32847038, 2020). "Next, we investigated whether CXCL13 expression influences the migratory activity of osteosarcoma tumor cells." (PMID 32847038, 2020). "We first applied CXCL13 to human osteosarcoma cell lines and examined cell motility." (PMID 32847038, 2020). "Incubation of osteosarcoma cells with CXCL13 increased VCAM-1 expression." (PMID 32847038, 2020). "However, little is known about the CXCL13/CXCR5 signaling axis in osteosarcoma." (PMID 32847038, 2020). "However, the effect of CXCL13 in the motility of osteosarcoma cells remains uncertain." (PMID 32847038, 2020). "The human osteosarcoma cell lines U-2 OS, 143B, and Mg63 highly expressed MICA/B and CXCL13, thus presenting a perfect avenue for the present study." (PMID 39450160, 2024). "Our qRT-PCR analysis demonstrated that osteosarcoma cells expressed higher levels of CGNL1 and CXCL13 compared to osteoblast cells, while ZNF583 had the opposite effect, indicating its potential as a novel anti-oncogene." (PMID 37980450, 2023). "Our study identified that CXCL13/CXCR5 axis facilitate VCAM-1 production and cell migration in human osteosarcoma via the phospholipase C beta (PLCβ), protein kinase C α (PKCα), c-Src, and nuclear factor-κB (NF-κB) signaling pathways." (PMID 32847038, 2020).
osteosarcoma (continued). "Here, we report that the CXCL13/CXCR5 interaction promotes the migratory and invasive potential of human osteosarcoma cells, which in turn mediates the phospholipase C β (PLCβ), protein kinase C α (PKCα), c-Src, and nuclear factor-κB (NF-κB) pathways." (PMID 32847038, 2020). "In this study, we found that CXCL13 facilitates PLCβ, PKCβ, and c-Src phosphorylation, while PLCβ, PKCα, and c-Src inhibitors reduce CXCL13-induced stimulation of VCAM-1 production and osteosarcoma cell migration." (PMID 32847038, 2020). "Incubation of all three osteosarcoma cell lines with PLCβ, PKCα, and c-Src inhibitors (U73122, GF109203X, and PP2, respectively) antagonized CXCL13-induced increases in cell migration and VCAM-1 production." (PMID 32847038, 2020). "Our study has identified that the CXCL13/CXCR5 axis facilitates VCAM-1 production and the migration of human osteosarcoma cells via the PLCβ, PKCα, c-Src, and NF-κB signaling pathways." (PMID 32847038, 2020). "This study provides the clinical insight that chemokine signaling pathway genes (CCL21, CCL22, CCL24, CXCL11, CXCL12, CXCL13, GNAI2, and RAC2) in proliferating cells might be the potential biomarkers for treatment of osteosarcoma." (PMID 37537613, 2023). "Treatment of human osteosarcoma cell lines (MG-63, HOS, and U2OS) with CXCL13 (3–30 ng/mL) concentration-dependently facilitated migratory and invasive abilities, but did not affect the viability of osteosarcoma cells." (PMID 32847038, 2020). "Therefore, the CXCL13/CXCR5 interaction regulates VCAM-1 synthesis and osteosarcoma cell migration." (PMID 32847038, 2020).
triple-negative breast carcinoma (8 papers, 2020 to 2025). An invasive breast carcinoma which is negative for expression of estrogen receptor (ER), progesterone receptor (PR), and human epidermal growth factor receptor 2 (HER2). "High levels of pre-treatment CXCL13+ T cells are associated with pro-inflammatory macrophage activity and predict favorable responses in patients with triple-negative breast cancer receiving paclitaxel combined with a PD-L1 monoclonal antibody." (PMID 40406143, 2025). "We found that GZMB+ CD8+ T cells from the immune-rich type had a higher expression of CXCL13, which was also reported to be associated with good responses to immunotherapies in triple-negative breast cancer." (PMID 36729271, 2023). "In a further study evaluating CXCL13 mRNA expression in the FinHER trial, CXCL13 as a marker of the humoral immune system was associated with favorable prognosis, particularly in triple-negative breast cancer (TNBC)." (PMID 33003293, 2020). "Furthermore, in a retrospective analysis of the FinHER trial, the B-cell attracting chemokine leukocyte chemoattractant–ligand (C–X–C motif) 13 (CXCL13) was independently associated with prognosis in triple-negative breast cancer." (PMID 33003293, 2020). "For example, CXCL13+ T cells were reported to predict an effective PD-L1 blockade response in triple-negative breast cancer." (PMID 38478516, 2024). "In addition, CXCL13-expressing CD8+ T cells are linked to the proinflammatory features of macrophages and show enhanced cytotoxicity following anti-PD-L1 therapy in triple-negative breast cancer." (PMID 34947813, 2021). "For example, B cell-attracting C-X-C motif chemokine ligand 13 (CXCL13)-positive, CD4-positive T follicular helper T (Tfh) cells were independently associated with distant disease-free survival (DDFS) in patients with triple-negative breast cancer (TNBC) in the FinHer trial patient population." (PMID 34298839, 2021).
myeloma (7 papers, 2015 to 2025). "Studies of multiple myeloma have shown that CXCL13 levels are elevated in the blood and bone marrow of patients." (PMID 41446602, 2025). "This was shown to not only lead to CXCL13 driven myeloma growth but also to contribute to receptor activator of nuclear factor (NF) kΒ ligand (RANKL)-mediated osteoclastogenesis." (PMID 40136679, 2025). "In line with earlier cancer research, the CXCL13 chemokine is crucial for the initiation and development of a variety of human malignancies like Waldenström macroglobulinemia and multiple myeloma." (PMID 37946029, 2024). "Based on these observations, and taking into account the known pro-myeloma role of macrophage-produced TGFβ, we evaluated the possible involvement of TGFβ signaling in macrophage-mediated induction of CXCL13 in MM cells." (PMID 36217194, 2022). "Characterization of cross-talk mechanisms between malignant human myeloma cells and BM microenvironment in xenograft MM model identified an enrichment of CXCL13-expressing M2-macrophages in the BM infiltrated by MM." (PMID 36217194, 2022). "First, mouse hybridoma was produced by fusing myeloma cells with splenocytes from a mouse immunized with human CXCL13." (PMID 25879435, 2015). "In addition to the regulation of B lymphocytes, CXCL13 has been reported to be involved in the M2 macrophage polarization and tumor progression in myeloma osteolytic." (PMID 37936696, 2023). "Subsequently, we evaluated murine CXCL13 levels following anti-myeloma therapy with bortezomib." (PMID 36217194, 2022). "Furthermore, significantly elevated murine CXCL13 levels were detected in peripheral blood and BM of myeloma-inoculated animals and correlated with tumor burden." (PMID 36217194, 2022). "Importantly, RPMI8226-CXCR4 myeloma cells were found to express high levels of human CXCL13." (PMID 36217194, 2022). "Zhang found that mesenchymal stem cells (MSCs) could secrete a large amount of CXCL13 in the bone marrow microenvironment of multiple myeloma and promote the proliferation, metastasis and drug resistance of myeloma cells through a CXCL13-mediated signaling pathway." (PMID 33110086, 2020). "Recent studies in tumors, such as multiple myeloma and glioblastoma, have shown positive relations between CXCL13 and CD206+ M2 macrophages, supporting the notion that CXCL13 has chemotaxis to CD206+ M2 macrophages in the BAT which may play a beneficial role in brown adipocytes thermogenesis." (PMID 37936696, 2023).
non-Hodgkin lymphoma (7 papers, 2010 to 2023). Distinct from Hodgkin lymphoma both morphologically and biologically, non-Hodgkin lymphoma (NHL) is characterized by the absence of Reed-Sternberg cells, can occur at any age, and usually presents as a localized or generalized lymphadenopathy associated with fever and weight loss. "CXCL13 secretion was seen in FL cells, and higher serum CXCL13 levels for more than 3 years have been associated with an increased risk of development of HIV-associated non-Hodgkin lymphoma." (PMID 37304286, 2023). "Another report demonstrated higher serum CXCL13 levels for more than 3 years increased the risk of development of HIV-associated non-Hodgkin lymphoma." (PMID 37304286, 2023). "Therefore, it seems reasonable to suggest that several cytokines, including CXCL13, can be upregulated in non-Hodgkin lymphoma." (PMID 37304286, 2023). "In addition, a more recent survey including 67 immune and inflammation markers between 301 patients with non-Hodgkin lymphoma diagnosed 5+ years after blood collection showed that higher serum CXCL13 level predicts future occurrences of DLBCL." (PMID 37304286, 2023).
Obesity (7 papers, 2013 to 2026). Accumulation of substantial excess body fat. "We illustrated the immune function of CXCL13 in adipose tissue and provided a promising therapeutic target from ASCs on obesity." (PMID 37936696, 2023). "In the context of obesity-related metabolic inflammation, CXCL13 acts as a central hub of immunometabolic dysregulation, driving pathological processes across multiple organs with significant organ- and stage-specific heterogeneity, which reflects spatiotemporal heterogeneity." (PMID 41885315, 2026). "This review systematically elucidates the pivotal role of CXCL13 in obesity-related metabolic inflammation, providing a theoretical foundation for the development of precision intervention strategies tailored to disease subtypes, stages, and specific organ targeting." (PMID 41885315, 2026). "The decreased expression of downregulated DEGs enriched in Ca2+ metabolism, including CXCL10, CXCL13, and PDE1C, as identified in this study could play a role in obesity and its associated complications by lowering Ca2+ levels." (PMID 39609876, 2024). "Therefore, CXCL13 may integrate the detrimental effects of obesity-induced pathological events on adipose tissue function." (PMID 39151591, 2024). "CXCL13 administration could be a novel therapeutic strategy for obesity." (PMID 37936696, 2023). "The expression of CXCL13 and its receptor CXCR5 are elevated in both subcutaneous white adipose tissue (SWAT) and visceral adipose tissue (VAT) under hypoxic conditions and in individuals with obesity." (PMID 37936696, 2023).
pancreatic ductal adenocarcinoma (7 papers, 2018 to 2025). An infiltrating adenocarcinoma that arises from the epithelial cells of the pancreas. "Furthermore, CXCL13 increases the expression of EVT4 in pancreatic ductal adenocarcinoma (PDAC), and EVT4 promotes PDAC invasion and metastasis by binding to CXCR5 on the tumor cell surface." (PMID 40406143, 2025).
prostate tumors (7 papers, 2013 to 2025). "Taken together, these results suggest that HFD-induced increases in the production of soluble factors (MCP-1, CXCL1, CXCL2, and CXCL13) play important roles in the stimulation of prostate tumor progression in mice." (PMID 25912035, 2015). "Thus, the results indicated that the high expression of CXCL13 was significantly correlated with prostate tumor in clinic, and the expression of CXCL13 might be up-regulated by androgen/AR axis." (PMID 28881808, 2017). "We have previously shown that PCa cell lines and prostate tumors express CXCR5 and respond to CXCL13 that is significantly elevated in the serum of PCa patients compared to serum of patients." (PMID 31628349, 2019). "Furthermore, we established a role for CXCL13 and CXCR5 interaction in prostate tumor progression and elucidated some of the molecular and cellular processes mediated by activation of this chemokine receptor." (PMID 23773523, 2013).
ulcerative colitis (7 papers, 2017 to 2026). An inflammatory bowel disease involving the mucosal surface of the large intestine and rectum. "CXCR5 and CXCL13 expression were also readily detected in gut associated lymphoid tissue (GALT) and lymphoid aggregates in gut samples of ulcerative colitis patients." (PMID 28827539, 2017).